EGFR (epidermal growth factor receptor)
Diseases named in the same sentence as EGFR in open-access papers (continued):
Sharing a sentence is not in itself a finding about the gene and the disease.
tumor (continued). "However, there is a certain relationship between the acquired resistance of EGFR-TKIS and c-MET gene amplification in about 20% of tumor cell lines without c-Met gene amplification." (PMID 34122599, 2021). "This resulted in the tumor sample failing to meet the sensitivity limit of the Oncomine Dx Target Test, the discordant results between the Oncomine Dx Target Test and the PNA‐LNA PCR clamp test, and the lack of response to EGFR‐TKI." (PMID 33314600, 2021). "Conjugation of the EGFR inhibitor, cetuximab, with a NIR fluorophore, has recently been found to be safe and effective in distinguishing tumor in both contrast-enhancing and non-contrast-enhancing tumor regions with a good signal to noise background." (PMID 33440712, 2021). "However, unlike in our study, they did not provide the QALY gained and ICER of anti-EGFR mAb compared to Bev in different scenarios of KRAS WT, pan-RAS WT, and pan-RAS left-sided tumor population to justify their conclusion." (PMID 34012917, 2021). "In a subsequent study, dual targeting of EGFR and CDK4/6 by erlotinib and palbociclib, respectively, is additively effective in reducing tumor growth in TNBC xenografts and PDX cells expressing MMP17, EGFR, and RB, whereas PDX-TNBC cells without RB expression were resistant to this combination." (PMID 34207383, 2021). "EGFR-CAR-T showed no preference to the tumors at the left or right and only partially inhibited tumor growth at both sides, which were supported by both the tumor isotope imaging and volume measurements." (PMID 34553036, 2021). "It is interesting to note that EGFR is expressed on intratumoral vessels but not vessels in non-tumor tissues, which would suggest that EGFL7 binding to EGFR could drive tumor-angiogenesis." (PMID 33804387, 2021). "Concomitant use of an EGFR inhibitor with an ICB might not be effective, as the tumor lacks immune infiltration and requires time to develop an immune response." (PMID 35008514, 2021). "However, most NSCLC patients are EGFR or ALK negative, and less than one-third of advanced lung tumors express PD-L1 in more than 50% of tumor cells." (PMID 34834454, 2021). "A retrospective qualitative evaluation on 71 LGG reported EGFR amplification being almost exclusively seen in IDHwt-LGG and significantly correlating with mild (not avid) contrast enhancement, with >5% enhancing tumor, and with infiltrative/mixed growth pattern." (PMID 33498680, 2021). "Tumor cells resistant to the EGFR inhibitor Erlotinib displayed enhanced Hedgehog signaling in the form of GLI1 expression and traits of EMT that were independent of EGFR." (PMID 34771518, 2021). "Taken together, the combination of anti-EGFR antibodies and interleukin may enhance ADCC in the tumor microenvironment, even in the absence of a direct antitumor effect by anti-EGFR antibodies." (PMID 34207383, 2021). "Our choices of tumor models for these experiments, PSMA-expressing 22Rv1 cells or PC3-PSMA cells, express high levels of hTfR and PSMA (>10-fold staining as assessed by aptamer staining using flow cytometry), but low or no levels of EGFR and PTK7." (PMID 34725326, 2021). "Similarly, a comprehensive whole-genome, transcriptome and clinical dataset called the POG570 cohort, had revealed that alterations in EGFR, ADGRG6, and other genes were involved in tumour drug resistance and sensitivity, as well as recurrent noncoding events." (PMID 34809653, 2021). "Another preclinical research showed that erlotinib inhibited tumor growth and metastasis in a SUM149 xenograft mouse model, which might be non-specific effect of EGFR inhibition since erlotinib could inhibit other kinases." (PMID 34778045, 2021).
tumor (continued). "However, amplification of EGFR, MET, and PIK3CA appear to be subclonal, in which all 3 oncogenes are coamplified within the same tumor cells as opposed to being each individually amplified across mutually exclusive clonal populations." (PMID 32338752, 2020). "Here, we observe that cetuximab alone does not alter NK cell infiltration of the MOC2-huEGFR tumor or reduce growth of this tumor, but is capable of eliciting ADCC against HNSCC tumor cells independent of its roles in blocking EGFR signaling or enhancing radiosensitivity." (PMID 33281820, 2020). "EGFR, VEGF-A and L1CAM appeared to be unsuitable targets, as their high non-specific background staining in tumor-negative tissues could significantly affect the accurate visualization of tumor tissue during surgery." (PMID 32545676, 2020). "Based on KEYNOTE‐042 (NCT02220894), pembrolizumab is approved as the first-line treatment of stage III NSCLC patients with no epidermal growth factor receptor (EGFR) or anaplastic lymphoma kinase (ALK) genomic aberrations, while also the tumour must express PD-L1 (TPS ≥1%)." (PMID 33574895, 2020). "In other words, in EGFR mutant tumors, PD-L1 expression is not the result of an immune process (i.e., upregulation induced by IFN-γ produced as result of an ongoing immune response), but is a mechanism of tumor immune escape." (PMID 33276569, 2020). "Since ADP, ATP and adenosine are known to induce transactivation of the mitogenic receptor EGFR, we hypothesised that ADP may induce prosurvival signals in tumour cell lines, but not in hTERT-HPNE, which expresses a relatively low level of P2Y12 and EGFR." (PMID 31968611, 2020). "For EGFR/ALK negative patients, anti-tumor treatments still rely on the traditional chemotherapy." (PMID 33285759, 2020). "Additional experiments could be performed to determine lapatinib-mediated reduction of expression of phosphorylated proteins in tumor cells such as HER2, EGFR, AKT, ERK1/2 in the presence or absence of adipocyte conditioned medium." (PMID 32795383, 2020). "SAH-JGZ4 administration inhibited tumor growth of NCI-H460 cells but not NCI-H157 and NCI-H2170 cells, suggesting that tumors with high expression of both TRIB3 and EGFR would be sensitive to SAH-JGZ4 treatment." (PMID 32694521, 2020). "Consistent with previous studies, SUVmax as a single pixel value only showed moderate AUC for distinguishing mutant EGFR from wild type in our study, whereas total lesion glycolysis (TLG) as a volumetric measurement of tumor glucose metabolism showed no higher predictive performance either." (PMID 33134170, 2020). "We showed that AZD8186 exerted its anti‐tumor function in vitro due to PI3Kβ inhibition, since PTEN‐null TNBC cells do not express appreciable levels of p110δ and the specific inhibition of p110α in combination with EGFR did not produce the same effects." (PMID 32672423, 2020). "In our experiments, the supplementation of TNuF inhibited EGFR, the downstream signaling protein STAT3, and the mitosis marker Ki-67, and upregulated the inhibitor PTEN, but did not influence chaperon protein HSP90 in LLC tumor cells." (PMID 32872195, 2020). "This previous study demonstrated that, in tumors displaying epidermal growth factor receptor (EGFR) amplification, the FAP+ perivascular population lacked EGFR amplification, thereby identifying them as a stromal cell type rather than a subtype of tumor cells residing in the perivascular niche." (PMID 33082953, 2020). "Employing tumor-fibroblast co-culture models, we demonstrate the importance of the RGD motif for efficient transduction in 2D through the epithelial cell adhesion molecule (EpCAM), but not the epidermal growth factor receptor (EGFR)." (PMID 31811202, 2019). "Moreover, according to tumor cell type, positive and negative correlation between the levels of RND1, and the sensitivity to EGFR inhibitors can be found." (PMID 31344837, 2019).
tumor (continued). "The phase III KEYNOTE-024 trial showed pembrolizumab as new standard first-line treatment in advanced NSCLC with high PD-L1 expression, defined as expression in at least 50% of tumor cells, tumor proportion score (TPS) ≥50%, and absence of EGFR or ALK aberrations." (PMID 31179334, 2019). "Moreover, the expression of other histopathological parameters such as EGFR, VEGF, and NOTCH1 differ between p16 positive and negative tumors, which suggest differences in tumor angiogenesis in these entities." (PMID 30718984, 2019). "First of all, because both maintenance treatment arms contained panitumumab, we could not investigate the predictive role of tumor sidedness and PRESSING panel status with regard to anti-EGFR therapy." (PMID 31539295, 2019). "In placebo fed mice, castration did not significantly affect EGFR or HER2 levels in the tumour; however, among those bearing 22Rv1 tumours and treated with lapatinib, HER2, but not EGFR levels were elevated in castrated mice, compared to intact mice (p = 0.005)." (PMID 31209328, 2019). "Unlike EGFR, which was abundantly expressed on both cultured and tumor cells, surface PRL3 was poorly expressed on cultured cells, yet expressed on most tumor cells (1.1% vs. 64.9% respectively)." (PMID 31171773, 2019). "Our data showed that the injection of CAR-EXO-CTX notably inhibited the growth of tumours derived from MDA-MB-231 cells, whereas combined treatment of the exosomes with EGFR-Fc protein antibodies, but not with IgG isotype antibodies or HER2-Fc protein, reversed the effect." (PMID 31554797, 2019). "In LG1179 (Kras G13R; Kras mutants are typically non-responsive to EGFR TKIs), one 1.5 mg/kg dose of RN765C resulted in sustained tumor regression while multiple doses of carboplatin were ineffective and gemcitabine only moderately slowed down tumor growth." (PMID 30323890, 2018). "The administration of the pembrolizumab molecule as first-line therapy to patients without genomic alterations in the genes EGFR, ALK, ROS1 and BRAF, and for whom 50 % of the tumor cells express PD-L1, has given back IHC a primordial role in the therapeutic care of patients with NSCLC." (PMID 29534030, 2018). "While application of precision medicine with therapeutics targeting RTKs yields dramatic responses in LUADs bearing oncogenic EGFR, ALK and ROS1, chronic control or cures have not yet been realized due to the inevitability of acquired resistance leading to tumor relapse." (PMID 29458371, 2018). "This may influence the molecular characterization of tumor tissue, now mandatory for patients with metastatic CRC who are candidates for treatment with an anti-EGFR mAb, as false-negative results can occur, leading to non optimal therapy." (PMID 30477151, 2018). "Tumor tissues had a rising trend of MSI1 mRNA expression from a poorly to well-differentiated state, showing the importance of MSI1 in the differentiation process, but there was not a similar trend for EGFR expression and tumor grade." (PMID 30202417, 2018). "EGFR deletion in myeloid cells did not affect OS development in terms of differences in tumor number, burden or serum ALP levels, suggesting that EGFR expression in myeloid cells, which include bone‐resorbing osteoclasts, is dispensable during c‐Fos‐induced OS formation." (PMID 30361264, 2018). "Patients with an identified driver EGFR, ALK or ROS1 should not receive first line ICIs even though tumor cells may express high PD-L1." (PMID 29890761, 2018). "In vivo, the combination of systemic gefitinib and a GLUT1 inhibitor, both of which failed to inhibit tumor growth when administered alone, significantly inhibited the growth of xenograft tumors formed by the implantation of NSCLC cells with wild-type EGFR (wt-EGFR)." (PMID 30220973, 2018). "Additionally, HER2 amplification detected on tissue or on circulating tumor DNA (ctDNA) was identified as a possible mechanism of acquired resistance in HER2 negative, RAS/BRAF WT, patients progressed during anti-EGFR treatment." (PMID 34532592, 2018).
tumor (continued). "However, EGFR TKI therapy results in responses of variable depth and duration and is not curative because complete tumor eradication is never achieved." (PMID 30097569, 2018). "The binding specificity to EGFR and death receptors was retained in all IgG-scTRAIL formats and translated into high antigen-specific bioactivity on EGFR-positive Colo205, HCT116 and WM1366 tumour cell lines, with or without sensitization to apoptosis by bortezomib." (PMID 29773864, 2018). "However, a contradictory result was obtained in a separate study, which showed that, even in the EGFR-mutant group, patients with an MPA tumor component still had a worse prognosis than patients without an MPA component." (PMID 29137260, 2017). "EGFR expression and signalling is elevated in cells lacking the WT FLCN tumour suppressor." (PMID 28656962, 2017). "While this assay was not analytically validated here for the determination of copy number variation, outlier coverage suggested amplification of EGFR in HCC827, which has been previously reported, and deletion of PTEN in “Biopsy 2” used for frozen tumor mixes (not confirmed)." (PMID 29100271, 2017). "Tumor volume at the end of the study (day 21) showed a highly significant growth inhibition with the EGFR BiTE® vs. MEC14 control BiTE® for implants with EGFR-positive cells or mixed EGFR-positive and -negative tumor cells, but not for implants containing only EGFR-negative tumor cells." (PMID 28837681, 2017). "In these triple-negative breast tumors the effect is likely to be entirely attributable to EGFR inhibition, and was reflected by significant inhibition of pEGFR by gefitinib treatment in HCC1806 tumor tissue, although the inhibition by gefitinib alone was not significant in MDA-MB-468 tumors." (PMID 28778177, 2017). "However, since clinical studies have shown that not all tumours are sensitive to EGFR inhibition and that others may develop acquired resistance, we suggest that a better understanding of the molecular mechanisms involved in EGFR-resistance is crucial to developing optimal therapeutic approaches." (PMID 31093349, 2017). "Accordingly, a minor fraction of CTSB-overexpressing cells in ParvOryx-treated patients displayed a non-macrophage EGFR-positive phenotype, suggesting that endogenous CTSB induction may also contribute to tumor cell killing." (PMID 28967558, 2017). "The infusion was safe without evidence of off-tumor toxicity or CRS and no cross-reactivity to wild type EGFR, except one patient developed non-convulsive status epilepticus 9 days after infusion, which was resolved with standard treatment and anti-cytokine therapy." (PMID 28466386, 2017). "Interestingly, in our study, using the same cell lines, EGFR and PODXL were expressed in cells from the primary tumour, but not in the metastatic cell line." (PMID 27160084, 2016). "However, patient age, menopausal status, primary node status, residual tumor grades, CK5/6 and EGFR were not significant variables." (PMID 27426056, 2016). "Osimertinib has greater penetration of the mouse blood–brain barrier than gefitinib, rociletinib, or afatinib, and induced sustained tumor regression in an EGFR mutant PC9 mouse brain metastasis model at clinically relevant doses, while rociletinib did not achieve tumor regression." (PMID 28149837, 2016). "Moreover, the results from cohort 2 differed somewhat in that high EGFR expression was an independent prognostic factor in PODXL low, but not high, tumours." (PMID 27160084, 2016). "EGFR, PTEN, cMET and AXL expression did not correlate with tumor response." (PMID 27028852, 2016). "Cetuximab enhanced the cytotoxic activity of NK cells on EGFR+ tumor cells (either RASwt, RASmut or BRAFmut) in a CD16 dependent manner, whereas it could not increase the killing of EGFR- COLO320." (PMID 27314237, 2016).
tumor (continued). "This suggests that determining EGFR overexpression of tumours only by IHC, without knowledge of the EGFR GCN, may be an inadequate method for selecting patients for anti-EGFR therapy." (PMID 27387915, 2016). "This tumor was found to be KRAS and BRAF wild type, and EGFR was not overexpressed." (PMID 26909603, 2016). "For example, modifications of EGFR and PIK3CA were almost clonal in tumour S6T1 but absent in S6T2." (PMID 27377421, 2016). "Therefore it is likely, that the produced amphiregulin is provided for other cell types of the tumor stroma, which did not get in contact with HGF before or amphiregulin is provided for cell types, where the EGFR is not blocked by HGF." (PMID 25884419, 2015). "However, recent studies identified that tumours with a KRAS wild type (KRAS WT) and positive EGFR expression as measured by IHC was not predictive of anti-EGFR efficacy." (PMID 26149458, 2015). "After labeling IFIT3 with the STrEP Tag, protein complexes that formed after interaction of IFIT3-StrEP with proteins from the tumor cell lysate stained positive for JNK and STAT1 by Western Blot analysis, while other typical signaling proteins such as Akt, EGFR, MAPK and Src were not detectable." (PMID 25650658, 2015). "Quantitative imaging phenotypes may be a surrogate marker for the tumor’s molecular makeup and allow for the identification of tumors that express VEGF, EGFR, or CD24, regardless of qualitative imaging features." (PMID 26207380, 2015). "Due to the focus on hallmarks and due to space constraints, we were not able to cover fully the extensive field of tumour imaging using tumour-specific markers, for example somatostatin receptors (SSTR), epidermal growth factor receptors (EGFR) and oestrogen receptors." (PMID 25673052, 2015). "Although the sequence of EGFR-TKIs in EGFR-mutant NSCLC may not affect the OS, the tumor response rates to second-line EGFR-TKIs are usually lower than to first-line use." (PMID 25552401, 2015). "EGFR inhibition did not change the expression of CD80, CD86, or PD-L1 on the tumor cells." (PMID 25240937, 2014). "It is noted that other miR-7 targets, such as EGFR and PI3K were not down-regulated in miR-7 treated EC based on the RNA-seq analysis, suggesting that the anti-proliferative activity of miR-7 occurs through other pathways in EC than in tumor cells." (PMID 25149532, 2014). "Multi-arm preclinical trials in MET-positive CRC cell lines and patient-derived xenografts revealed that long-lasting abolition of tumor growth could be achieved through MET inhibition, with or without concurrent interception of EGFR." (PMID 24811491, 2014). "Thus, the present review of EGFR-TKI retreatment is focused mainly on those patients who need new systemic treatment and excludes those with slowly progressing tumor, oligometastases or isolated CNS metastases." (PMID 25563355, 2014). "Tumor cells were negative for CEA, AR, ER, PR, EGFR, and Her-2/neu oncoprotein." (PMID 23419146, 2013). "The tumor cells immunolabeled with GFAP and IDH1, and were negative for EGFR." (PMID 24252196, 2013). "Tumor cells were negative for CK20, AR, ER, PR, EGFR, and Her-2/neu oncoprotein." (PMID 23419146, 2013). "Furthermore, several co-expression pairs have been repeatedly described, mainly between VEGF, COX-2, EGFR, and LMP1, which were not prominent in our tumor series." (PMID 23360534, 2013).